PLK4 (polo like kinase 4)
Diseases named in the same sentence as PLK4 in open-access papers (continued):
Sharing a sentence is not in itself a finding about the gene and the disease.
cancer (continued). "Due to its key role in tumor growth and development, PLK4 is considered one of the most promising therapeutic targets in cancer." (PMID 35670224, 2022). "In recent years, due to key roles of PLK4 in the progression of cancers, several PLK4 inhibitors have been identified, but the clinical therapeutic effects on cancers were still unsatisfactory (Holland and Cleveland." (PMID 36051696, 2022). "Due to the vital roles of PLK4 in the regulation of centrosome replication and the pathology of cancers, more and more PLK4 inhibitors were developed, such as Centrinone, Centrinone-B, CFI-400495 and YLT-11." (PMID 36051696, 2022). "A research study conducted by ESTIMATE demonstrated a correlation between high PLK4 expression and immune cell and stromal cell infiltration across a wide range of cancers." (PMID 36620611, 2022). "PLK4 can also regulate cancer cells invasion and metastasis via mediating the events of actin cytoskeleton." (PMID 35387563, 2022). "Accordingly, our results indicate that PLK4 is aberrantly expressed in a wide range of cancers, and influences cancer patients’ prognoses." (PMID 36620611, 2022). "To better understand the impacts of PLK4 expression in various cancers, we analyzed the correlation between PLK4 expression levels and the prognosis of patients with different tumors." (PMID 36620611, 2022). "Some studies have shown that the high PLK4 expression is positively correlated with low survival rates for lung cancer and can promote the invasion and metastasis of cancer." (PMID 36176741, 2022). "A second inhibitor, CFI-400945, described as a potent and selective PLK4 inhibitor, was found effective in cancers, and taken into clinical trials." (PMID 35053604, 2022). "Recently, PLK4 was illustrated to regulate the phosphatidylinositol 3-kinase (PI3K)/protein kinase B (Akt) signaling pathway to play its role in cancers." (PMID 35387563, 2022). "In this study, we comprehensively characterized the PLK4 expression and its correlation with the prognosis of tumor patients in pan-cancer." (PMID 36620611, 2022). "The PLK4 mRNA expression was significantly negatively correlated with its methylation level, which was significantly lower in cancer tissues at various pathological stages and tumor grades, than in normal tissues." (PMID 36176741, 2022). "PLK4 is the keystone centrosomal duplication protein and increased expression of PLK4 has been reported in cancers originating from different tissues and organs including colon, stomach, breast, prostate, and brain." (PMID 35053604, 2022). "ESTIMATE, immune, and stromal scores correlate negatively with PLK4 expression in most TCGA cancers." (PMID 36620611, 2022). "Many studies have shown that PLK4 is expressed at abnormal levels in various cancer types, but different levels in different cancer types." (PMID 36176741, 2022). "Targeting the diverse functions of PLKs (tumor suppressor, oncogenic) are currently at the center of numerous investigations in particular with the inhibition of PLK1 and PLK4, respectively in multiple cancer trials." (PMID 34065956, 2021). "Further translational research is warranted, especially as PLK4-selective inhibitors have recently been developed and applied in clinical tests for cancer therapy." (PMID 33778212, 2021). "In this section, we summarize recent studies on the correlation between Plk4 and the hallmarks of cancer." (PMID 33777739, 2021). "The phosphorylated Arp2 was activated and promoted cell motility, suggesting that Plk4 facilitates invasiveness and metastasis of cancer cells via activating the ARP2/3 complex." (PMID 33777739, 2021).
cancer (continued). "In this review, we summarized the regulation of Plk4 at the DNA, RNA, and protein levels, as well as the roles of Plk4 in cellular processes that are involved in human cancer." (PMID 33777739, 2021). "Collectively, these findings indicate that Plk4 plays a pivotal role in cancer invasion and metastasis." (PMID 33777739, 2021). "These contradictory correlations point to PLK4 possibly acting as a tumor promoter as well as a tumor suppressor depending on cancer biology." (PMID 34065956, 2021). "Preclinical data showed that targeting Plk4 is a promising therapeutic intervention in a subset of human cancers that express a high level of Plk4." (PMID 33777739, 2021). "Future investigations are needed to better our understanding of the mechanisms of Plk4 in cancer development and the efficacy and potential resistance of Plk4 inhibitors." (PMID 33777739, 2021). "In conclusion, we highlight the importance of PLK4 as a therapeutic target in DLBCL and emphasize the need of combining PLK4 inhibitor with genotoxic drugs for cancer treatment." (PMID 34162828, 2021). "In a recent report in cancer research, PLK4 was found to play a role in cytoskeleton reorganization and lamellipodia formation in HeLa cells, and the authors used the result to explain the PLK4 function in cancer cell migration." (PMID 33778212, 2021). "PLK4 is also part of WNT signaling pathways involved in the regulation of cancer cell motility and invasiveness." (PMID 34065956, 2021). "In all, for different reasons, both high and low expression levels of Plk4 have been found in HCC and are associated with clinical parameters, such as prognosis and cancer progression." (PMID 33777739, 2021). "Growing evidence indicates that PLK4 is overexpressed in many subtypes of cancer and high expression of PLK4 confers poor prognosis." (PMID 34162828, 2021). "Both Plk1 and Plk4 have been investigated as potential targets in anticancer therapies as inhibition of their activity induces cell death in cancer cells." (PMID 32060361, 2020). "Restoration of FAM46C function warrants investigation as a therapeutic strategy in treatment-resistant cancers driven by Plk4." (PMID 32807875, 2020). "Mechanistically, PLK4 functionally targets the Arp2/3 complex, and a physical and functional interaction between PLK4 and Arp2 drives PLK4-driven cancer cell movement." (PMID 32501498, 2020). "FAM46C restrains centriole duplication and cancer cell invasion in opposition to Plk4, and acts as a tumor suppressor in a human cancer xenograft model." (PMID 32807875, 2020). "Out of the five members of the Plk family, Plk1 and Plk4 are considered as promising targets in cancer therapies due to their important functions as kinases during the cell cycle of tumor cells." (PMID 32060361, 2020). "It induced polyploidy that led to apoptosis of cancer cells by interfering with the mitotic checkpoint kinase BubR1, which is likely to be a result of its PLK4 inhibition." (PMID 31035676, 2019). "The favourable PK characteristics and evidence of preliminary antitumour activity support the further development of this agent and validate PLK4 as a potential therapeutic target in cancer patients." (PMID 31303643, 2019). "To further validate the oncogenic effects of PLK4, we investigated the effects of PLK4 on cancer cell functions in HCC cell lines." (PMID 31489978, 2019). "KLF14, which is often downregulated in human carcinomas, has a function in maintaining the integrity of centrosomes by limiting Plk4 (Polo-like kinase 4) transcription, which is a master regulator of centriole duplication and assembly." (PMID 31406196, 2019). "Abnormal expression of PLK4 has been reported in many human cancers, and inhibition of PLK4 activity results in their mitotic arrest and apoptosis." (PMID 30337519, 2018). "Overexpression of PLK4 is frequently detected in many metastatic human cancers and connected with cancer progression or poor prognosis." (PMID 30337519, 2018).
cancer (continued). "In summary, we reported here that YLT-11 is a novel and specific small-molecule inhibitor in cancer therapy with a mechanism of action that involves valid suppression of PLK4 activity." (PMID 30337519, 2018). "The aberrant expression of PLK4 was found in several cancers and a recent study has unraveled a novel function of PLK4 as a mediator of invasion and metastasis in Hela and U2OS cells." (PMID 29352113, 2018). "Overexpression of PLK-4 has been reported for a variety of neoplasms, indicating its oncogenic role in cancer progression." (PMID 30315225, 2018). "The proposed role of PLK4 in the regulation of cytokinesis and maintenance of chromosomal stability is consistent with a function in cancer, as centrosome amplification can drive genetic instability with a resultant impact on tumorigenesis." (PMID 29340047, 2017). "The fact that non-neoplastic proliferating cells seem to be “resistant” to CFI-400945-induced polyploidy supports the rationale for cancer therapy by PLK4 inhibitors." (PMID 29340047, 2017). "Although PLK4 inhibition would be expected to disturb mitosis in normal cells, potentially this would be more severe in chromosomally-unstable cancers, providing a clinically-useful therapeutic window." (PMID 27902970, 2017). "Cancer cell lines with supernumerary centrioles treated with a specific inhibitor of the centriole assembly regulator Polo-like kinase 4 (Plk4) showed a reduction in centriole number due to cell division in the absence of centriole assembly." (PMID 27904881, 2016). "As KLF14 inhibition promotes Plk4 transcription, we suggest KLF14 reduction contributes to Plk4 overexpression in human cancers." (PMID 26439168, 2015). "Oncomine data analysis revealed that multiple human cancers are coincident with increased Plk4 transcription and decreased KLF14 transcription." (PMID 26439168, 2015). "To address the long-known relationship between supernumerary centrosomes and cancer, we have generated a transgenic mouse that permits inducible expression of the master regulator of centriole duplication, Polo-like-kinase-4 (Plk4)." (PMID 26701933, 2015). "Results revealed that PLK4 expression was mainly present in the cytoplasm of cancer cells Scattered staining of PLK4 in nuclear was also observed." (PMID 22829937, 2012). "Consequently, PLK4 has emerged as a viable therapeutic target for cancer management, with ongoing clinical trials of PLK4 inhibitors for the treatment of cancer." (PMID 41488365, 2025). "In addition, targeted inhibition of PLK4 has emerged as a promising therapeutic strategy in the fight against cancer, supported by recent preclinical studies investigating the synthetic‐lethal relationship between TRIM37 amplification and PLK4 inhibition." (PMID 40257113, 2025). "Hence, targeting PLK4 can be beneficial for the management of nervous system tumors, subject to additional detailed studies in this area in human-relevant cancer models." (PMID 41488365, 2025). "Preclinical studies have produced highly encouraging results, indicating that PLK4 inhibition could be a valuable addition to cancer treatment." (PMID 40710347, 2025). "Yet, these inhibitors have played a significant role in elucidating the role of PLK4 in cancers." (PMID 41488365, 2025). "Too much PLK4 activity would initiate excessive centriole duplication, which could lead to multipolar spindles and aneuploidy, two hallmarks of cancer cells." (PMID 40710347, 2025). "However, the in-depth understanding of signaling pathways and the regulation of PLK4 in cancers continues to evolve." (PMID 41488365, 2025). "Since we found that CDK2 antagonism opposed centrosome clustering, combining such an inhibitor with a PLK4 inhibitor that we reported to promote supernumerary centrosomes could reduce proliferation and augment apoptosis in polyploid cancer cells." (PMID 40232858, 2025).
cancer (continued). "And indeed, PLK4 inhibitors could selectively reduce centrosome amplification and subsequent aneuploidy, making them attractive candidates for targeted cancer therapies." (PMID 40710347, 2025). "It was reported that using PLK4 inhibitors could improve the efficacy of cancer treatments by reducing the number of centrosomes, thereby enhancing patient outcomes." (PMID 40710347, 2025). "Synthetic lethal relationships can also help to select cancers for treatment with PLK4 inhibitors." (PMID 40710347, 2025). "Further translational and clinical studies of PLK4 inhibitors would provide a foundation for the development of novel biomarkers and effective treatment strategies in this, one of the most morbid and lethal cancer types in women worldwide." (PMID 41092110, 2025). "Multiple investigations have been conducted to define the role and significance of PLK4 in cancer." (PMID 41488365, 2025). "Importantly, cancers with amplified TRIM37 became increasingly vulnerable to PLK4 inhibition, which led to mitotic failure or death." (PMID 40257113, 2025). "It is plausible that regulation of PLK4 by NF-κB could be a key pathway that contributes to genomic instability in cancer, either driven by inflammation or oncogenic signals." (PMID 41488365, 2025). "Notably, KAT2B co-acetylates PLK4 with KAT2A at K45/K46 sites, suppressing its kinase activity to prevent centrosome amplification leading to cancer-associated chromosomal instability." (PMID 40495188, 2025). "Targeting PLK4 for the treatment of cancers has proven to be an efficient strategy." (PMID 40710347, 2025). "Notably, the fast-track designation and encouraging preclinical results of CFI-400945 highlight the promise of PLK4 inhibitors as next-generation cancer therapeutics." (PMID 41488365, 2025). "Currently, there is no direct evidence linking PLK4-induced primary cilia loss to cancer and requires detailed investigation." (PMID 41488365, 2025). "A potential synergistic effect between immune checkpoint inhibitors and PLK4 inhibition, which through DNA replication errors, can generate neoantigens, might also be promising in cancer treatment." (PMID 41092110, 2025). "Importantly, pharmacological inhibition of PLK4 has demonstrated tumor-suppressive effects in various cancer models." (PMID 40940791, 2025). "Similarly, the strategy of PLK4 inhibition for cancer management is currently being actively investigated." (PMID 41488365, 2025). "Our data suggest a model whereby the combined action of PLK4 inhibition and RT leads to increased overamplification of centrioles, which in turn increases genomic instability, compromises the ability of cancer cells to cope with genotoxic stress and results in enhanced anticancer effects." (PMID 38365710, 2024). "Collectively, targeting the Vpr C-terminal motif could be an attractive strategy to antagonize the function of the Vpr•VprBP•Plk4 complex and thereby reduce the occurrence of HIV-1-associated cancers." (PMID 38443376, 2024). "The over-expression of PLK4 is a double-edged sword for cancer cells, as it can provide an advantage in promoting genomic instability, while also having the potential to form multipolar metaphases due to extra centrosomes, which can result in uneven cell division." (PMID 38388511, 2024). "Nonetheless, targeting PLK4 has emerged as promising strategy for anti-cancer treatments." (PMID 39285247, 2024). "Second, Nemo-like kinase (NLK), Polo-like kinase 4 (PLK4) and TTK (alias MPS1) were identified in synthetic lethal screens in PTEN-deficient cancer cells and may warrant further investigation in LMS." (PMID 38473300, 2024).
cancer (continued). "Polo-like kinase 4 (Plk4), the major regulator of centriole biogenesis, has emerged as a putative therapeutic target in cancer due to its abnormal expression in human carcinomas, leading to centrosome number deregulation, mitotic defects and chromosomal instability." (PMID 36797240, 2023). "CFI-400945 is known to target PLK4 and regulate centriole duplication of cancer cells." (PMID 36750553, 2023). "Moreover, we also show that cells with high Plk4 expression secrete factors that promote anoikis resistance of cancer cells in a paracrine way, being P-cadherin one of the mechanistic players in that process." (PMID 36797240, 2023). "Moreover, we also observed that cancer cells treated with the conditioned media of cells with both Plk4-overexpressed and silenced P-cadherin presented a decreased capacity to form mammospheres, but they still have higher MFE than control cells." (PMID 36797240, 2023). "The methylation level of PLK4 was higher in high-grade tumors and advanced cancer stages." (PMID 36176741, 2022). "A series of studies indicated that PLK4 promoted the progression of cancers." (PMID 36051696, 2022). "Recent studies have shown that PLK4 is an important antiapoptotic molecule in cancer cells." (PMID 35670224, 2022). "Firstly, we determined whether PLK4 expression in pan-cancers was correlated with the ESTIMATE scores (ESTIMATE, immune, and stromal scores)." (PMID 36620611, 2022). "We therefore speculated that Fraxetin may exert its anti-cancer effect through down-regulating PLK4 expression." (PMID 35387563, 2022). "The summary of the structure, studied cancer cells and roles of the inhibitors of PLK4." (PMID 36051696, 2022). "Although many studies have been done on roles of PLK4, there was a controversy in whether PLK4 promoted or suppressed the progression of cancers." (PMID 36051696, 2022). "Previous studies have elucidated a variety of additional functions for PLK4 in cancers." (PMID 36620611, 2022). "We found few publications investigating the role of PLK4 from a pan-cancer perspective." (PMID 36620611, 2022). "However, although many databases—such as the Cancer Genome Atlas (TCGA), the Gene Expression Omnibus (GEO), and the Genome-Tissue Expression (GTEx) database—exist, few studies have examined the pan-cancer carcinogenic effects of PLK4." (PMID 36620611, 2022). "Furthermore, the increased kinase activity of PLK4 in cancer cells suppressed caspase‐9‐ and caspase‐3‐mediated apoptosis, whereas decreased expression of PLK4 potentiated apoptosis." (PMID 35670224, 2022). "PLK4 can regulate the PI3K/Akt signaling pathway to play its role in cancers." (PMID 35387563, 2022). "A recent paper identified the ubiquitin ligase TRIM37 as responsible for cancer-specific vulnerability to PLK4 inhibition, and identification of vulnerability hot spots could help PLK4 targeting in cancers." (PMID 35053604, 2022). "Thus, to elucidate roles and mechanisms of PLK4 in the progression of cancers was important for the new drug design and screen." (PMID 36051696, 2022). "Although it has been reported that PLK4 downregulation may contribute to cancer cell death, but the possible mechanisms are unknown." (PMID 35387563, 2022). "Furthermore, changes in the genetic and epigenetic background in cancers can lead to the overexpression of centrosome duplication factors, such as PLK4, STIL, and HsSAS-6, which leads directly to CA by overproducing new centrioles." (PMID 35053604, 2022).